GAPDHP24 (glyceraldehyde 3 phosphate dehydrogenase pseudogene 24)
Gene: Processed pseudogene on chromosome 1 (214,870,734 to 214,871,716, forward strand). Ensembl gene ENSG00000185221.
Diseases named in the same sentence as GAPDHP24 in open-access papers:
GAPDHP24 is named in the same sentence as 1 disease in open-access papers, as found by Europe PMC text mining. Sharing a sentence is not in itself a finding about the gene and the disease. The quoted sentences say what the papers report.
infection (1 paper, 2019). The state of being infected such as from the introduction of a foreign agent such as serum, vaccine, antigenic substance or organism. "Subsequently, when HSP90B1 with GAPDHP24-induced phosphorylation further triggers the regulation of TF ETS1, HSP90B1 with ubiquitination will not activate TF ETS1 in the infection of C. albicans SC5314." (PMID 30769958, 2019).